SIM1 (SIM bHLH transcription factor 1)
Diseases named in the same sentence as SIM1 in open-access papers (continued):
Sharing a sentence is not in itself a finding about the gene and the disease.
Obesity (continued). "Some of the genes associated with monogenetic severe obesity are: leptin (LEP), leptin receptor (LEPR), proopiomelanocortin (POMC), MC4R, preproconvertase 1 (PCSK1), single minded 1 (SIM1), brain-derived neurotrophic factor (BDNF), and tyrosine kinase receptor tropomycin-related kinase B (TrkB)." (PMID 32982666, 2020). "However, heterozygous Sim1+/– mice are viable, presenting an early-onset obesity, hyperphagia, and increased linear growth, similar to Mc4r-mutant mice." (PMID 32982666, 2020). "Sim1-Cre is expressed in other brain regions in addition to the PVH40, so the obesity phenotype in Sim1-Cre;Ntrk2lox/lox mice might result from Ntrk2 deletion in non-PVH neurons or cells." (PMID 32265438, 2020). "Mutations in genes coding for SIM1, BDNF, and TRKB appear to be involved in the development of obesity in both mice and humans, although the regulatory mechanisms are still unknown." (PMID 33261141, 2020). "A recent study published in Science safely targeted the non-coding genomic region of Sim1 and MC4R with rAAV packed with CRISPRa, and successfully rescued the obesity syndrome caused by haploinsufficiency in a murine model, which shed light on their potential therapeutic applications in the future." (PMID 31124015, 2019). "However, heterozygous mice (Sim1 +/-) develop partial failure of hypothalamic neurons resulting in hyperphagia and obesity similar to mc4r-mutant mice." (PMID 30991789, 2019). "Hypothalamic Sim1 overexpression rescued diet-induced obesity due to reduced food intake." (PMID 31124015, 2019). "As it has been proved that haploinsufficiency of SIM1 is related to obesity in genetic studies, it is plausible that methylation in SIM1 may contribute to reduced SIM1 expression, and through which related to obesity." (PMID 30765773, 2019). "Mice with global MRAP2 deletion and conditional MRAP2 deletion in SIM1 expressing neurons developed marked obesity, while rare loss-of-function or missense heterozygous variants in MRAP2 were identified in humans with severe early-onset obesity." (PMID 30352741, 2018). "Similar mechanisms operate for other obesity genes such as SIM1." (PMID 28859103, 2017). "In contrast to SIM1, there have been no reports to date of obesity associated with OTP mutations or haploinsufficiency." (PMID 29107289, 2017). "It contributes to the regulation of human weight and has also been reported to be abnormally inactivated in obesity mouse model, implying that the inactivation of SIM1 may accompany the initiation and progression of obesity." (PMID 29258237, 2017). "For example, mutations in SIM1, leptin receptor (LEPR), pro-opiomelanocortin (POMC), melanocortin 4 receptor (MC4R), and more recently, POU3F2 have all been associated with severe obesity, suggesting a convergence on the leptin-melanocortin pathway in association with oxytocin." (PMID 27857842, 2016). "In the example of Sim1, heterozygous knock outs of this gene survive, but develop severe obesity associated with increase in food intake without measurable energy expenditure." (PMID 25825681, 2015). "However, Sim1 heterozygotes were viable but developed early-onset hyperphagic obesity with clinical features of metabolic syndrome." (PMID 22043167, 2011). "These factors might contribute to the variable expressivity and penetrance of SIM1-related obesity." (PMID 41516406, 2026). "Therefore, the activation of SIM1 or MC4R expression may represent a potential cure for inherited forms of obesity." (PMID 40650152, 2025). "Mutation of SIM1 is not always responsible for a fully penetrant form of obesity." (PMID 40428410, 2025). "Although functional and genetic studies investigating the combined effects of mutations in both the SEMA3-PLXNA pathway and SIM1 have not yet been conducted, the convergence of their roles in hypothalamic development strongly suggests a synergistic impact on obesity risk." (PMID 40428410, 2025).
Obesity (continued). "Although these genes have not been linked directly to CVD, they are linked to CVD risk factors; SIM1 has a role in neuronal differentiation of the hypothalamus, which is critical for food consumption regulation, and loss-of-function mutations in SMI1 associate with increased risk of obesity." (PMID 39187864, 2024). "Other loci which have been implicated in severe childhood monogenic obesity include genes of the proopiomelanocortin (POMC), the melanocortin receptor 4 (MC4R), the protein convertase 1/3 (PC 1/3), the single-minded homolog 1 (SIM1), and the brain-derived neurotrophic factor (BDNF)." (PMID 36452324, 2022). "UBC-cre/ERT2; mir-7fl/fl mice displayed a more pronounced obesity phenotype than Sim1-cre;mir-7fl/fl mice, suggesting that miR-7 in other unidentified cell population(s) or an additive effect of miR-7 in multiple hypothalamic cell types may be implicated in weight regulation." (PMID 36175420, 2022). "Comparing the body weight of AAV-injected Sim1-cre mice versus AAV-injected wild-type littermates, we found that overexpression of Snca and Igsf8 caused an exacerbation of HFD-induced obesity, whereas overexpression of Spata2, Pole4, Fndc4, Smim12, or Arrb1 had no impact on body weight." (PMID 36175420, 2022). "However, three genes, i.e., SIM1, BDNF, and tropomyosin-related kinase B (TRKB), when mutated, cause obesity, although the exact mechanisms by which these genetic defects lead to obesity are still unknown." (PMID 33261141, 2020). "Therefore, hyper-methylation in SIM1, which may result in a repression of gene expression and consequently SIM1 insufficiency, could relate to obesity." (PMID 30765773, 2019). "Of note, heterozygous loss of function mutations in the transcription factor SIM1, which plays a very similar and overlapping role in the development of neurons in the PVN of the hypothalamus, are more prevalent and associated with hyperphagia, severe obesity and behavioral abnormalities." (PMID 29107289, 2017). "Our findings support previous evidence that SIM1 disruptions lead to PWL phenotypes, including hyperphagia, early-onset obesity, and developmental delay." (PMID 41516406, 2026). "However, only a limited subset of these loci has shown consistent associations with obesity development after rigorous multiple corrections or validation in different populations, for instance, lymphocyte antigen 86 (LY86) methylation and single-minded homolog 1 (SIM1) methylation." (PMID 40302954, 2024). "Interestingly, Sim1 haploinsufficiency disrupts lineage specification by compromising the generation of a subset of neurons (e.g., oxytocin+ and vasopressin+ cells) and augmenting another subset of neurons, which may thereby lead to hyperphagic obesity." (PMID 36214963, 2023). "Transgenic mice expressing human MCHR2 have reduced food intake and body weight, whereas humans with deletions encompassing MCHR2 and an adjacent gene, Single-Minded Homolog 1 (SIM1), have increased appetite and obesity." (PMID 35271580, 2022). "We found that Sim1 cell-specific CRTC1 and CRTC2 double-knockout mice were sensitive to high-fat diet (HFD)-induced obesity." (PMID 35020776, 2022). "Ablation of single-minded homolog 1 (SIM1)-positive neurons, a marker of PVN neurons, leads to hyperphagia (over-eating) and obesity." (PMID 33668705, 2021). "The genes in the top 2 enriched regions for monogenic obesity were Pomc, Pcsk1, and Lepr in ARH, and Sim1, Pomc, and Tub in THy/PHy." (PMID 34283813, 2021). "Rare familial monogenic obesity syndromes have been informative in elucidating underpinnings of obesity, demonstrating roles for genes such as SIM1 and TUB in obesity." (PMID 30563851, 2018). "The mutation in the Mc4r gene produces a premature stop codon, and the mutant SIM1 protein lacks transcriptional activity, showing that the haploinsufficiency of SIM1 and MC4R results in obesity." (PMID 27585985, 2016).
Obesity (continued). "Heterozygous Sim1+/– mice exhibit a small PVN with reduced neuronal number and develop severe early-onset obesity due to hyperphagia and increased linear growth." (PMID 27106110, 2016). "At least two CNVs, of SIM1 at 6q16 and BDNF at 11p14, are well known to include obesity as a phenotype." (PMID 25411582, 2014). "Conditional deletion of Sim1 after gestational development of the PVN also results in both a reduction in oxytocin mRNA expression, and in hyperphagia and obesity." (PMID 23518828, 2013). "Transcripts for several candidate genes for obesity were absent in the whole brain or absent in specific regions of the brain (Cyp17a1, Gdf15, Gpr151, Lmx1b, Olig3, Sbk1, Sim1, Skor1, Tnni3k)." (PMID 39920851, 2025). "SIM1 haploinsufficiency (SIM1+/−) leads to obesity, marked by hyperphagia without reduced energy expenditure, underscoring SIM1’s role in energy homeostasis and the leptin–melanocortin–oxytocin pathway." (PMID 40428410, 2025). "This study demonstrates that miR-7 is required for the sexual dimorphism of body weight control, as female mice lacking miR-7 in Sim1 neurons exhibit enhanced obesity and ultimately attain the same body weight as male mice." (PMID 36175420, 2022). "As SCN disruption leads to metabolic dysfunction and obesity, loss of miR-7 in this hypothalamic region may account for the stronger obesity phenotype of UBC-cre/ERT2;miR-7fl/fl mice compared to Sim1-cre;miR-7fl/fl mice." (PMID 36175420, 2022). "Disruption of Sim1 expression in adult mice leads to increased food intake and obesity, suggesting that Sim1's effects on energy homeostasis are not confined to its role in hypothalamic development." (PMID 29107289, 2017). "Unlike obesity in Sim1 or Mc4r mutant mice, the obesity induced in the high-fat diet rodent model is relevant to human obesity which is strongly associated with the recent availability of high-calorie food." (PMID 27585985, 2016). "In contrast, mice overexpressing Sim1 do not increase their food intake when given a high-fat diet, and are resistant to diet-induced obesity." (PMID 23518828, 2013). "Overexpression of Sim1 partially rescues agouti yellow obesity by normalizing food intake without altering feeding efficiency, a marker of energy expenditure." (PMID 22558467, 2012). "In support, mice (Sim1-Cre:Bdnf lox/lox) with BDNF depletion in Sim1+ cells, which blanket the PVN and represent several molecularly defined neuronal subpopulations, exhibit hyperphagia, obesity, glucose intolerance, and hyperinsulinemia compared to control littermates fed a chow diet." (PMID 38672441, 2024). "Despite their obesity, we found increased levels of growth hormone (GH) mRNA and protein in the pituitary, as well as increased insulin-like growth factor 1 (IGF-1) protein levels in the liver and plasma of Sim1-cre;mir-7fl/fl mice compared to mir-7fl/fl controls." (PMID 36175420, 2022). "As ARNT2 is enriched in neurons, and Arnt2−/− mice phenocopy the loss of PVH neurons observed in Sim1−/− mice, it is hypothesized that disruption of the SIM1/ARNT2 axis drives obesity in humans with or without clinical features that are also described in Prader-Willi-like (PWL) syndrome." (PMID 32932609, 2020). "Besides SIM1 and MC4R, the haploinsufficiency of proprotein convertase 1 (PCSK1), melanocortin 2 receptor accessory protein 2 (MRAP2) in the brain, iroquois homeobox 3 (IRX3) in fat or uncoupling protein 3 (UCP3) in mitochondria are also responsible for human obesity." (PMID 31124015, 2019).
developmental delay (6 papers, 2014 to 2026). "Deletions and SNVs of SIM1 are associated with hyperphagic obesity, with developmental delay associated with 6q14.1 deletions." (PMID 28859103, 2017). "We are the first to report that head MRI, peripheral nerve conduction studies, and auditory brainstem response are normal in patients with developmental delay due to a 6q16.1 deletion that does not contain the SIM1 gene." (PMID 35581197, 2022). "There is only one report of patients with developmental delay due to a 6q16.1 deletion that does not contain the SIM1 gene." (PMID 35581197, 2022).
Hyperinsulinemia (6 papers, 2013 to 2025). An increased concentration of insulin in the blood. "Sim1- and MC4R-expressing neurons control insulin secretion by regulating autonomic tone, and deficiency of Sim1 or MC4R results in hyperinsulinemia in mice and humans." (PMID 36175420, 2022).
metabolic syndrome (3 papers, 2011 to 2025). A cluster of metabolic risk factors for CARDIOVASCULAR DISEASES and TYPE 2 DIABETES MELLITUS. "None of the previous studies reported the appearance of metabolic syndrome among the SIM1 mutation carriers." (PMID 28472148, 2017).
breast carcinoma (2 papers, 2010 to 2016). "These included genes/loci previously reported to be methylated in breast cancer (for example SIM1, PAX6, DLX4, RUNX3)." (PMID 20205715, 2010).
erectile dysfunction (2 papers, 2022 to 2025). Persistent or recurrent inability to achieve or to maintain an erection during sexual activity. "In all analyses, the strongest effect variants mapped to a non-coding region known to regulate SIM1, previously associated with erectile dysfunction: rs78677597 (Europeans) (p = 5.32 × 10−139), and rs17185536 (Africans (p = 1.17 × 10−9) and cross-ancestry (p = 5.3 × 10−138))." (PMID 41285899, 2025). "The transcription factor Single-Minded Family BHLH Transcription Factor 1 (SIM1) has recently been linked to erectile dysfunction in humans, but in mouse models the direct knockout of the SIM1 gene has yet to be assessed for erectile dysfunction." (PMID 36301850, 2022).
hypopituitarism (2 papers, 2025). A condition of diminution or cessation of secretion of one or more hormones from the anterior pituitary gland. "These potentials roles are supposed in several mice studies, while hypopituitarism seemed to be due to the association of SIM1 with other variants, such as POU3F2 gene mutations." (PMID 40428410, 2025). "There have been reported cases of Prader–Willi syndrome and hypopituitarism in patients with chromosomal deletions containing the SIM1 gene." (PMID 40429924, 2025).
morbid obesity (2 papers, 2014 to 2017). An excess of body weight, normally defined as an individual with a body mass index greater than 35 or a body weight greater than one hundred percent of ideal body weight. "Recently we have found a number of Loss of Function (LoF), non-synonymous variants of SIM1 in a cohort of children displaying early onset, morbid obesity." (PMID 24465693, 2014).
Rett syndrome (2 papers, 2015 to 2022). A severe neurodevelopmental disorder affecting the central nervous system.
Anorexia (1 paper, 2012). Lack of desire to eat (loss of appetite). "We reported previously that Sim1 deficiency resulted in reduced oxytocin expression and impaired melanocortin-mediated anorexia as well as PVH neuron activation." (PMID 22558467, 2012).
cervical cancer (1 paper, 2022). A primary or metastatic malignant neoplasm involving the cervix. "Single-minded homolog 1 (SIM1) was mentioned in only two studies so far for cervical cancer tissue." (PMID 35725812, 2022).
epilepsy (1 paper, 2013). A brain disorder characterized by episodes of abnormally increased neuronal discharge resulting in transient episodes of sensory or motor neurological dysfunction, or psychic dysfunction. "Moreover, the genes RELN and SIM1, regulated by PLZF overexpression, are involved in epilepsy and mental retardation, respectively." (PMID 23469216, 2013).
gastric tumors (1 paper, 2019). "IRF7, SIM1, IFNG, and HNF1A were predicted to be upstream regulators of the higher expressed genes in the EBV negative gastric tumors involved in cellular movement, inflammatory response, and immune cell trafficking." (PMID 31584998, 2019).
hypothyroidism (1 paper, 2026). Abnormally low levels of thyroid hormone. "Notably, some of our patients exhibited endocrine abnormalities, including hypothyroidism and hypothalamic dysfunction, consistent with earlier reports of patients with SIM1 deficiency." (PMID 41516406, 2026).
nutritional diseases (1 paper, 2017). "SIM1 has been reported to be related to appetite disorders, a specific subtype of nutritional diseases, because of its potential contribution to nutritional disease." (PMID 29258237, 2017). "In addition to NROB2, another protein, namely, SIM1 (ENSP00000262901), is also a potential regulator that contributes to the pathogenesis of the nutritional disease." (PMID 29258237, 2017).
infection (1 paper, 2021). The state of being infected such as from the introduction of a foreign agent such as serum, vaccine, antigenic substance or organism. "It would be interesting to study the SIM1 further by infection studies." (PMID 34055792, 2021).
tumor (1 paper, 2016). "Similarly, 45/49 and 36/48 LAC cases compared to 3/31 and 0/31 tumor-adjacent normal lung samples showed hypermethylation of the SIM1 and HOXB3/HOXB4 regions, respectively." (PMID 27782156, 2016).
SIM1 also shares sentences with these, for which no sentence is quoted: Prader-Willi-like syndrome (3 papers); autism (2); cancer (2); Anxiety (1); astrocytoma (1); Bardet-Biedl syndrome (1); behavioral disorders (1); central obesity (1); diabetes insipidus (1); dilated cardiomyopathy (1); Glucose intolerance (1); Huntington disease (1); Hypertension (1); Impaired glucose tolerance (1); Insulin resistance (1); muscular dystrophy (1); neurodevelopmental disorder (1); skin cancer (1).